SULT4A1 (sulfotransferase family 4A member 1)
Description:
Atypical sulfotransferase family member with very low affinity for 3'-phospho-5'-adenylyl sulfate (PAPS) and very low catalytic activity towards L-triiodothyronine, thyroxine, estrone, p-nitrophenol, 2-naphthylamine, and 2-beta-naphthol. May have a role in the metabolism of drugs and neurotransmitters in the CNS.
Synonyms: hBR-STL-1; NST; SULTX3; BR-STL-1; BRSTL1; DJ388M5.3
Tractability: PROTAC: its protein half-life has been measured.
Target class: Enzyme; Transferase
Gene: Protein-coding gene on chromosome 22 (43,824,509 to 43,862,513, reverse strand). Ensembl gene ENSG00000130540.
Subcellular location: Cytoplasm
Pathways (Reactome):
Metabolism: Cytosolic sulfonation of small molecules
Gene Ontology:
Molecular function: identical protein binding; protein binding; sulfotransferase activity
Biological process: sulfation; dendrite arborization
Cellular component: cytosol; cytoplasm; mitochondrion
Genetic constraint (gnomAD): Loss-of-function variants: 11 observed, 28.3 expected, observed/expected ratio (o/e) 0.39, 90% interval 0.24 to 0.64. The upper end of that interval is the gene's LOEUF score, 0.64, which puts it in group 2 of 6, group 1 being the genes least tolerant of losing a copy. Missense variants: 271 observed, 330.23 expected, observed/expected ratio (o/e) 0.82, 90% interval 0.74 to 0.91. Synonymous variants: 152 observed, 129.26 expected, observed/expected ratio (o/e) 1.18, 90% interval 1.03 to 1.35.
Homologues: Orthologues: chimpanzee SULT4A1 (99% identical), macaque SULT4A1 (99% identical), mouse Sult4a1 (98% identical), rat Sult4a1 (98% identical), guinea pig SULT4A1 (96% identical), dog SULT4A1 (89% identical), rabbit SULT4A1 (88% identical), zebrafish sult4a1 (87% identical), pig SULT4A1 (82% identical), tropical clawed frog sult4a1 (78% identical), Drosophila melanogaster St4 (34% identical), Drosophila melanogaster St3 (29% identical), and 1 more. Paralogues in human: SULT1A3 (37% identical), SULT1A4 (37% identical), SULT1A1 (35% identical), SULT1A2 (35% identical), SULT1C4 (35% identical), SULT1E1 (34% identical), SULT1B1 (33% identical), SULT1C2 (32% identical), SULT2B1 (32% identical), SULT1C3 (30% identical), SULT2A1 (30% identical), SULT6B1 (25% identical).
Diseases named in the same sentence as SULT4A1 in open-access papers:
SULT4A1 is named in the same sentence as 20 diseases in open-access papers, as found by Europe PMC text mining. Sharing a sentence is not in itself a finding about the gene and the disease. The quoted sentences say what the papers report.
schizophrenia (6 papers, 2014 to 2024). A major psychotic disorder characterized by abnormalities in the perception or expression of reality. "Its high expression in specific regions of the brain suggests a role for SULT4A1 in the central nervous system and has been implicated in schizophrenia." (PMID 36118903, 2022). "The only clinical manifestations that might be correlated with the SULT4A1 polymorphism/haplotype are the psychopathological disorders Phelan–McDermid syndrome and schizophrenia." (PMID 39062693, 2024). "Polymorphisms in the SULT4A1 gene have been linked to susceptibility to schizophrenia." (PMID 24988429, 2014). "Interestingly, a number of studies have demonstrated an association between specific single nucleotide polymorphisms in the SULT4A1 gene and susceptibility to schizophrenia." (PMID 24988429, 2014). "For example, SULT4A1 and SLC12A5 are associated with schizophrenia." (PMID 33423377, 2021). "However, a large retrospective analysis showed that the SULT4A1 haplotype is not significantly correlated with schizophrenia susceptibility and response to treatment." (PMID 39062693, 2024). "However, the SULT4A1 haplotype is correlated with Phelan–McDermid syndrome and schizophrenia." (PMID 39062693, 2024). "Disruption of SULT4A1 expression contributes to neurodevelopmental syndromes; Sequence polymorphisms in the 5’-UTR and haploinsufficiency of the SULT4A1 gene (deletions at loci 22q13.3) are associated with schizophrenia and Phelan-McDermid syndrome, an autism spectrum disorder." (PMID 35102205, 2022).
breast carcinoma (2 papers, 2024). "Based on our extensive search, it also identified several new potential genes associated with breast cancer progression, including HPCA, SLC9A2, SCNN1B, SULT4A1, and GUCY2D." (PMID 39768011, 2024).
cognitive deficits (2 papers, 2022 to 2025). "Additional genes from Regions 2 and 3 (PHF21B, SULT4A1, SCUBE1, and NUP50) we speculate that they may further contribute to cognitive deficits, neurodevelopmental features, and growth abnormalities." (PMID 40429797, 2025).
neuroblastoma (2 papers, 2022 to 2024). Neuroblastoma (NB) is the most common solid, extracranial childhood tumor. "Subsequently, it has been shown that the homologous expression of SULT4A1 in undifferentiated SH-SY5Y neuroblastoma cells protects against mitochondrial hydrogen-peroxide-induced oxidative stress and cell death." (PMID 39062693, 2024).
steatosis (2 papers, 2013 to 2024). Increased lipid within the cytoplasm of cells. "However, only two SULT isoforms, SULT1C4 and SULT4A1, whose regulation and function are largely unknown, have increased mRNA and protein levels in human NASH samples compared to control and steatosis samples." (PMID 23346097, 2013).
brain tumor (1 paper, 2016). "Similarly, SULT4A1, with lower expression in children brain tumor, is regulated positively by NFIL3 in normal samples while negatively by NFIL3 in NG group." (PMID 27586240, 2016).
glioma (1 paper, 2017). A benign or malignant brain and spinal cord tumor that arises from glial cells (astrocytes, oligodendrocytes, ependymal cells). "Of these 8 genes, 6 (SULT4A1, NDRG4, GAP43, BEX1, HINT1, LZTS1) are believed to act as tumor suppressants, while the remaining two, PKM and VIPR1, have been found to be overexpressed in glioma." (PMID 28957313, 2017).
osteosarcoma (1 paper, 2021). A usually aggressive malignant bone-forming mesenchymal neoplasm, predominantly affecting adolescents and young adults. "Among them, the expression of MYH6 and SULT4A1 in osteosarcoma was higher than that in control group, while the expression of LIPE, ACTG2, KLF4, and TF was decreased." (PMID 34104648, 2021).
Phelan-McDermid syndrome (1 paper, 2022). A rare genetic neurodevelopmental disorder characterized by neonatal hypotonia, global developmental delay, normal to accelerated growth, absent to severely delayed speech, and minor dysmorphic features. "SULT4A1 gene deletion has also been linked to Phelan-McDermid Syndrome (PMS), a generalized cognitive and developmental autism spectrum syndrome." (PMID 35102205, 2022).
prostate carcinoma (1 paper, 2012). A carcinoma that arises from epithelial cells of the prostate gland. "The authors could link the enhanced prostate cancer risk after methyl bromide exposure with a SNP in rs93322959 gene coding for the microsomal GST1 enzyme (OR, 3.1; 95% CI (1.3-7.5) and SNP in rs5764318 of cytosolic sulfotransferase, SULT4A1 (OR, 2.2; 95% CI (1.0-4.5)." (PMID 22284215, 2012).
renal adysplasia (1 paper, 2022). "The SULT4A1, PARVB, SCO2, and UPK3A genes are associated with neurological features, macrocephaly/hypotonia, oculopathy, and renal adysplasia, respectively." (PMID 36118903, 2022).
thymoma (1 paper, 2021). A neoplasm arising from the epithelial cells of the thymus. "LIPE, MYH6, ACTG2, KLF4, SULT4A1, and TF were the key genes affecting the prognosis of thymoma." (PMID 34104648, 2021). "By screening the DEGs that had a significant impact on the prognosis of thymoma, we identified LIPE, MYH6, ACTG2, KLF4, SULT4A1, and TF as key genes." (PMID 34104648, 2021). "This study identified key genes related to the prognosis of thymoma, including LIPE, MYH6, ACTG2, KLF4, SULT4A1, and TF." (PMID 34104648, 2021). "ACTG2, KLF4, SULT4A1, and TF were all involved in the occurrence or development of cancer, but their biological significance in thymoma was not clear." (PMID 34104648, 2021).
tumor (4 papers, 2015 to 2025). "Other genes down-regulated in ATRX-altered tumours included USE1, SULT4A1 and the nuclear-encoded mitochondrial gene COX17." (PMID 38978571, 2024).
SULT4A1 also shares sentences with these, for which no sentence is quoted: astrocytoma (1 paper); cancer (1); Cirrhosis (1); Insulin resistance (1); pneumonia (1); schizotypal personality disorder (1); viral infection (1).